CXCL10 (C-X-C motif chemokine ligand 10)
Diseases named in the same sentence as CXCL10 in open-access papers (continued):
Sharing a sentence is not in itself a finding about the gene and the disease.
tumor (continued). "Moreover, we observed upregulated chemokines (such as CCL3/4/5 and CXCL10/11/12) expression in TeMs, suggesting the importance of tumor macrophages in recruiting T cells." (PMID 37488416, 2023). "Additionally, patients with a GWR of less than 60% or tumor recurrence had significantly elevated levels of MDSCs and CXCL10/TLR4." (PMID 37345131, 2023). "In addition, CXCL10 played an essential role in mediating the anti-tumor effect of anti-PD-1 treatment and also contributed essentially to the synergistic anti-tumor effects of thermal ablation and anti-PD-1 treatment." (PMID 36900218, 2023). "Therefore, CXCL10 induced via BCG administration is considered important for anti-tumor immune reactions." (PMID 38002062, 2023). "DPP4 enzymatic activity has been shown to reduce both T‐cell and eosinophil migration to sites of tumor by inactivating the T‐cell chemokine CXCL10[8b] and the eosinophil chemokine CCL11.[8c] Here, we extended these findings by showing the nonenzymatic activity of DPP4 in cell migration." (PMID 36683148, 2023). "Furthermore, tumor-infiltrating cDC1s can produce chemokines such as the CXC chemokine ligand (CXCL) 9 and CXCL10 to attract CD8+ T cells into the tumor microenvironment (TME), representing an essential role of DCs for cancer immunotherapy." (PMID 37514189, 2023). "We further speculated that the reduced efficacy of anti-PD-1 treatment in Cxcl10−/− mice might be related to the reduction in CD8+T cells in tumor tissues." (PMID 36900218, 2023). "Indeed, Falchook and colleagues showed upregulated CXCL10 mRNA levels in tumours of patients treated with RBN-2397, accompanied by an increase in CD8+ GZMB+ T cells." (PMID 37752135, 2023). "Therefore, it is possible that tumor-infiltrating myeloid cells are an important source of CXCL10 and CCL2 after short-course ATRi plus RT, and that prolonged daily ATRi negatively impacts these myeloid cells and reduces CXCL10 and CCL2 production." (PMID 36810257, 2023). "Directly targeting CAFs could also improve migration of immune cells to the tumor core by modulation of the CXCL10/CXCL9-CXCR3 axis." (PMID 38022679, 2023). "The upregulation of pro-inflammatory cytokines can also lead to the production of IFNγ which can induce chemokines CXCL9 and CXCL10 to recruit NK cells, neutrophils, macrophages, and T cells to the tumor and stimulate acquired immunity for a tumor-specific response." (PMID 37588093, 2023). "In addition, in the high glycolysis-cholesterol metabolic axis activated tumor, CXCL10 was potentially to be downregulated and thereby impairing the localization of T cells in TME." (PMID 37828561, 2023). "Similarly, immune/inflammation-related TFs, such as NFKB2, STAT1, and RELA, and FOXO3, showed high activity in CXCL10+MEL and TMSB4X+MEL subclusters, which underlies the immunomodulatory phenotype of tumor cells." (PMID 38065972, 2023). "It had been reported that CXCL10 was involved in tumor growth and metastasis, which may serve as a novel target for cancer treatment." (PMID 37903782, 2023). "pEMT-like tumor cells were prone to recruit PCs by secreting cytokines such as CXCL10 or CXCL11." (PMID 37138324, 2023). "In the process of tumor progression, studies have shown that CXCL10 has a dual role." (PMID 37109526, 2023). "Tumor necrosis is functionally mediated by infiltrating monocytes/macrophages, and it has been demonstrated that the mobilization of monocytic myeloid-derived suppressor cells (MDSCs) promotes tumor recurrence after liver transplantation via CXCL10/TLR4/MMP14 signaling." (PMID 36698095, 2023). "CXCL10 is an important angiostatic chemokine involved in tumour growth and new vessel formation." (PMID 37686338, 2023).
tumor (continued). "As a key modulator for chemoattraction of immune cells, promotion of T-cell function, and antitumor activity in the local TME38, CXCL10 may offer a surrogate for presuming the tumor immune subtype." (PMID 37880538, 2023). "CXCL10 is secreted by multiple cell types including monocytes, endothelial cells, fibroblasts, inflammatory cells, and tumor cells in response to interferon‐γ,25 and increased CXCL10 expression in tumor cells is important for anti‐tumor T cell responses." (PMID 38133557, 2023). "Instead, engineered T cells + CD40 agonist, which we previously showed to promote the persistence of engineered T cells in autochthonous PDA, promoted tumor cytoplasmic Cxcl9/Cxcl10, indicating that immunotherapy alters the subcellular localization of Cxcr3 ligands in tumor cells." (PMID 36472588, 2023). "In addition, due to knockdown of USP18, more T cell chemoattractant CXCL10 is generated in mammary epithelial cells, accompanied with creating a tumor-suppressive microenvironment by attracting CD4 + T cells." (PMID 37658402, 2023). "These associations may also reflect the suppression of local anti-tumour inflammatory response in necrotic tumours, considering that CXCL10 and IFNG are regarded as important cytokines in the antitumorigenic T helper type 1 response." (PMID 37031328, 2023). "Additionally, M1-polarized macrophages can recruit new Th1 cells via IFN-γ and chemokines CXCL9 and CXCL10 to kill tumor cells." (PMID 38001420, 2023). "The differential expression of Cxcl10 and Cxcl9 in tumor vs. spleen likely reflects different composition of myeloid cells and raises the possibility that the chemokines may play a differential role in the TEFF vs. TEX fate choice." (PMID 36472588, 2023). "In addition to deactivating local T cells, (D)-2-HG also diminishes the chemotaxis of immune cells to the tumor sites by inhibiting the secretion of C-X-C motif chemokine ligand 10 (CXCL10) by dendritic cells." (PMID 37546420, 2023). "Stimulator of interferon genes (STING) upregulation in tumor APCs triggers chemokine expression, notably C-X-C motif chemokine ligand 9 (CXCL9) and CXCL10 by DCs, and CXCL10 and CXCL11 by tumor-associated macrophages (TAMs), folstering intratumoral T cell trafficking." (PMID 38044445, 2023). "Previous studies reported that CXCL10 promoted the adhesion of metastatic cells to laminin and thus may antagonize the antitumor effects of chemokines on the tumor microenvironment." (PMID 36819776, 2023). "We, therefore, propose that serum CXCL10 concentrations may serve as a surrogate for tumor immune subtypes and that levels may fluctuate with serum CXCL9 concentrations, reflecting the extent of immune reconstitution by anti-angiogenic therapy." (PMID 37880538, 2023). "In contrast, tumor tissue staining by IF showed predominantly Cxcl10 + cells." (PMID 36472588, 2023). "Therefore, we assumed that the mechanism of ablation treatment enhancing anti-tumor immune response was regulated by the CXCL10/CXCR3 axis." (PMID 36900218, 2023). "Given the importance of CCL5 and CXCL10 in mediating an anti-tumor immune response, these findings raise additional hypotheses regarding the significance of OSA cell intrinsic STING expression to effect radiation immunomodulation in vivo." (PMID 37079538, 2023). "Cancer cells in which β-catenin signalling is activated have low chemokine (C-C motif) ligand 4 production and suppress the accumulation of conventional DC (cDC1), which produces chemokine (C-X-C motif) ligand 10 (CXCL10) in the tumour, thereby hindering T cell infiltration." (PMID 36298556, 2022). "In our study, we explore the effect of CXCL10 on persistent tumors, demonstrate that tumor and immune cells undergo crosstalk during EGFR-TKI treatment, and suggest that this crosstalk could impact the efficacy of EGFR-TKI treatment." (PMID 36612121, 2022).
tumor (continued). "Evidenced by the trend analysis, the functional enrichment and previous prognostic study, we inferred that the chemokine CXCL10 might play a crucial role in tumor microenvironment of NPC progression." (PMID 35433690, 2022). "In the tumor microenvironment, CXCL10 has been revealed to have anti-malignant properties." (PMID 35847936, 2022). "Further, CXCL10 has a potential role as an anti-tumor agent mediated by oncolytic viruses." (PMID 36366543, 2022). "Furthermore, the enhancement of anti-tumoral immune cells in tumor-bearing Cxcl10−/− mice induce a pro-inflammatory and therefore anti-tumorigenic microenvironment compared to corresponding tumor-bearing WT mice." (PMID 35897689, 2022). "Additionally, the levels of the chemokines CXCL9 (MIG, p < 0.0001, median 54.3 pg/mL vs 7.0 pg/mL) and CXCL10 (IP-10, p = 0.0021, median 92.9 pg/mL vs 16.7 pg/mL) were also increased in the tumor samples compared to the healthy tissues." (PMID 35927313, 2022). "We hypothesized that Tc17 cells may migrate to the tumor tissue, secrete CCL20 to recruit MoDCs, and then the activated DCs secrete CXCL10 to induce CD8+ T cell tumor infiltration, leading to inhibition of tumor growth." (PMID 35459193, 2022). "Finally, we performed qPCR validation in clinical tissue samples and showed highly expressed POSTN, VISG4 in tumor samples, and highly expressed CXCL10, CXCL13, and MMP12 in normal samples." (PMID 36212488, 2022). "The tumor suppressor function of CXCL10 and STAT2 is supported by several lines of evidence." (PMID 35207629, 2022). "Our data also indicate that CXCL10 significantly increases in stable and responding patients after the first month of therapy, suggesting that an initial activation of the immune system would be fundamental for effective treatment response and tumor clearance." (PMID 35361879, 2022). "Comparing immune cells and immune-related gene expression across different FAT statuses, we found that in FAT mutant STAD, chemokines, such as CCL3, CCL4, CXCL1, CXCL3, CXCL9, and CXCL10, recruited and activated cytotoxic T lymphocytes in the tumor tissue to perform an antitumor effect." (PMID 35836939, 2022). "However, contrary to what was mentioned in the part of T lymphocytes, CXCL9 and CXCL10 here induce tumor invasion indirectly." (PMID 35935996, 2022). "Indeed, our data from the characterization of CXCL9 and CXCL10 in the tumor location appears to be higher." (PMID 35459734, 2022). "The increased abundance of IFNγ secreting CD4+ TILs in CaMKK2-deficient mice, in addition to chemotactic signals from DC-like TAMs (Cxcl9, Cxcl10), may explain the enhanced tumor penetrance seen by CD4+ and myeloid cells in the setting of CaMKK2 deficiency." (PMID 36309495, 2022). "Furthermore, qRT-PCR analysis revealed a significantly elevated Afp expression as a marker of tumor cell de-differentiation in WT and Cxcl10−/− HCC tissue in comparison to the surrounding tissue." (PMID 35897689, 2022). "Notably, CXCL10 secreted due to anthracycline-induced ICD of tumor cells can recruit T cells to the TME." (PMID 36755812, 2022). "Furthermore, further studies are needed to investigate how the oncogenic signaling of CXCL10 affects the development of long-term resistance in persistent tumor cells that survive immediately after EGFR-TKI treatment." (PMID 36612121, 2022). "CXCL10 can induce monocyte and T-lymphocyte chemotaxis, leading to tumor suppression." (PMID 35222540, 2022). "CXCR3-CXCL9/CXCL10 chemokine axis is known for its tumor-inhibiting properties." (PMID 35320940, 2022). "Targeting MDSC mobilization via CXCL10/TLR4 signaling could not only protect the liver graft from IRI but also reduce tumor recurrence after transplantation." (PMID 35634295, 2022). "In addition, IP-10 (CXCL-10) which is an important chemokine ligand in recruiting anti-tumor Th1 cells and polarising the immune response to a Th1 phenotype, is significantly reduced perioperatively." (PMID 35154142, 2022).
tumor (continued). "Since tumorigenic Cxcl10−/− mice display a strong enhancement of anti-tumoral immune cells, we proceeded to profile whether these cells tip the balance of the tumor microenvironment to an overall anti-tumoral immune response." (PMID 35897689, 2022). "Moreover, KDM6B inhibit CXCL9 and CXCL10 expression in colon cancer and exerts an anti-tumor immune effects." (PMID 36713412, 2022). "CXCL9 and CXCL10 are involved in CD8+ T cells infiltrating into tumor tissues." (PMID 35359417, 2022). "EZH2 could also restrain the anti-tumor effect of macrophages and NK cells by suppressing the chemotaxis ability of tumors by reducing the expression level of CXCL10, CCL2, and other chemokines." (PMID 36552722, 2022). "We discovered that most of them were enriched in immune cells, immune molecules and immune-related signaling pathways, and the results were consistent with the previous literature that CXCL10 was involved in chronic inflammation, immune dysfunction and tumor development." (PMID 35083488, 2022). "The enhancement of αSMA+ cells at the tumor site of the DEN/CCl4-treated Cxcl10−/− mice suggests that these cells might be gaining a cancer-associated fibroblast-like (CAFs) function." (PMID 35897689, 2022). "It induces high amounts of CCL5 and CXCL10 in tumor cells with distinct kinetics." (PMID 36429101, 2022). "While the proportion of the TILs did not significantly differ between the cytokine highly and lowly expressing tumors, CXCL10 (IP-10) and CXCL9 (MIG), known to belong to the CXC chemokine subfamily were associated with increased lymphocyte quantities in the tumor samples." (PMID 35927313, 2022). "Therefore, we further explored the effect of CXCL10 on oncogenic signaling in persistent tumor cells in our system." (PMID 36612121, 2022). "However, subcutaneous injection of tumor cells transduced to overexpress CXCL10, which results in increased NK cell tumor infiltration, does increase overall survival as compared to control cell injection." (PMID 35844626, 2022). "We further analyzed the quantity of CD3 + T and NK cells out of all cells in the tumor samples and observed that CXCL10, and CXCL9 levels were significantly correlated with the number of tumor infiltrating CD3 + T cells; CXCL10 levels also correlated with the number of tumor infiltrating NK cells." (PMID 35927313, 2022). "It has been therefore suggested that the biological effect of CXCL10-mediated signalling varies depending on whether the receptor is expressed upon the tumour itself or the microenvironment." (PMID 35844527, 2022). "In addition, zeste homolog 2 (EZH2)-mediated histone lysine methylation and DNA methyltransferase-1 (DNMT-1)-mediated DNA methylation suppressed the production of CXCL9 and CXCL10 respectively, and then inhibited T-cell tumor homing." (PMID 35493527, 2022). "For example, recent studies have shown that the overexpression of CXCL10 can migrate tumor cells through the AKT and MEK signaling pathways to neurons, resulting in PC-associated neural invasion, and that chemokine blockers diminish this effect in an animal model." (PMID 35755810, 2022). "Additionally, CXCL10 has been shown to decrease estrogen-induced pro-tumor development by inhibiting VEGF production." (PMID 35982458, 2022). "Interestingly, comparison between both tissue types in the DEN/CCl4-treated WT and Cxcl10−/− mice revealed a reduced chemokines accumulation in WT tumor tissue compared to WT surrounding tissue." (PMID 35897689, 2022). "Tumor cell lines with high expression of CXCL10 exhibit suppressed growth." (PMID 35223493, 2022). "Proteins associated with tumor regression including granzyme A (GZMA) and Th1 markers such as the C-X-C motif chemokine ligand family (CXCL9, CXCL10, CXCL11) and interferon gamma (IFNG) mirrored the checkpoint inhibitor decreases seen in tissue during single agent pembrolizumab therapy." (PMID 36572780, 2022).
tumor (continued). "From this we could postulate that CCL17, CXCL1 and CCL2 act early and in a similar way to indirectly help tumour growth, possibly by upregulating CXCL10 production and myeloid cell expansion, which act more directly on tumour growth." (PMID 35226704, 2022). "Studies have shown that activated MCs can recruit tumour-infiltrating effector T cells and natural killer cells by secreting CXCL10 and CXCL8, respectively; in addition, mast cells can also greatly alter B cell generation, development, and function by secreting cytokines such as IL-6." (PMID 35610596, 2022). "In the in vitro tumor cell culture model, stimulation by L. paracasei sh2020 could result in the increased production of CXCL10, which was further confirmed by the L. paracasei sh2020-treated tumors in vivo." (PMID 35259052, 2022). "At the same time, it could augment the expression of IFN-γ and C-X-C motif chemokine ligand 10 (CXCL10) at the tumor zone." (PMID 35392976, 2022). "Furthermore, Cxcl10−/− impacts the tumor stoma composition, tumor cell proliferation and angiogenesis." (PMID 35897689, 2022). "In addition, IFN-β (p < 0.0004) and CXCL-10 (p < 0.0002) were also found to be upregulated by 4-fold upon dose-dependent treatment of AVA-NP-695 in the 4T1 tumor." (PMID 36235254, 2022). "Studies have shown that CXCL10 has dual effects on tumor progression." (PMID 36207693, 2022). "Moreover, high expression levels of CXCL10 and CXCL11 were associated with better PFI and early tumor stage in patients with CRC." (PMID 36003333, 2022). "As tumor CXCL10 and CXCL9 concentrations were correlated with the quantity of intratumoral lymphocyte and CD3 + T cells, we wanted to confirm whether the plasma levels of these cytokines would give some guidance to the tumor lymphocyte counts." (PMID 35927313, 2022). "However, emerging reports focused on tumor-promoting ability of CXCL10 by increasing cell proliferation and metastasis." (PMID 36207693, 2022). "Furthermore, the quantity of lymphocytes in the tumor samples analyzed with flow cytometry positively correlated with the chemokine-family of cytokines, CXCL10 (IP-10) and CXCL9 (MIG)." (PMID 35927313, 2022). "Moreover, VSV was identified in promoting inflammatory tumor cell killing via the release of chemokines, including CXCL10, which trigger the infiltration of T effector cells into the tumor growth sites." (PMID 36366543, 2022). "CXCL10 could then turn cold tumor into hot tumor, thus leading to improve efficacy of chemoimmunotherapy." (PMID 35529902, 2022). "CXCL10 has been recognized as a strong angiostatic factors, and it may participate in the recruitment of tumor-infiltrating T cells." (PMID 36544484, 2022). "CXCL10 has been regarded as having an anti-malignant role in the tumor microenvironment." (PMID 35847936, 2022). "Additionally, a novel CXCL10 fusion protein (IP10‐scFv) coadministered with CTLs successfully induced tumor‐infiltrating lymphocytes and prolonged survival in mice." (PMID 35702353, 2022). "CXCL10 is secreted by different types of cells such as leukocytes, monocytes, neutrophils, eosinophils, epithelial cells, endothelial cells, stromal cells and tumor cells." (PMID 35083488, 2022). "Furthermore, M1 macrophages express proinflammatory cytokines like TNFα, IL-6, and CXCL10, present antigen to immune cells and phagocytize tumor cells." (PMID 35419058, 2022). "Furthermore, tumor tissue of the Cxcl10−/− mice displayed a strong enhancement of cytotoxic cytokines (perforin and granzym B) in comparison to their WT counterparts, which is probably related to the increased number of cytotoxic CD8+ T cells and NK cells." (PMID 35897689, 2022). "Consistently, LLC and MC38 tumor-infiltrating CD11c+ MHCII+ CD11b+ Ly6c+ CXCL10+ DCs were significantly increased in CD45+ cells in the RORγt agonist-treated group compared with the vehicle group, and CCL20 levels were higher in RORγt agonist-treated tumor tissue compared to vehicle treated tumors." (PMID 35459193, 2022).